KHDC1 (KH domain containing 1)
Synonyms: C6orf147; C6orf148; MGC10818; bA257K9.4; NDG1; Em:AC019205.8
Tractability: Antibody: UniProt predicts a signal peptide or a membrane-spanning region.
Gene: Protein-coding gene on chromosome 6 (73,241,310 to 73,310,455, reverse strand). Ensembl gene ENSG00000135314.
Subcellular location: Membrane
Subcellular location (Human Protein Atlas): Cytosol; Vesicles
Gene Ontology:
Molecular function: RNA binding
Cellular component: cytoplasm; membrane
Genetic constraint (gnomAD): Loss-of-function variants: 21 observed, 25.48 expected, observed/expected ratio (o/e) 0.82, 90% interval 0.58 to 1.19. The upper end of that interval is the gene's LOEUF score, 1.19, which puts it in group 5 of 6, group 1 being the genes least tolerant of losing a copy. Missense variants: 274 observed, 309.84 expected, observed/expected ratio (o/e) 0.88, 90% interval 0.8 to 0.98. Synonymous variants: 98 observed, 114.88 expected, observed/expected ratio (o/e) 0.85, 90% interval 0.72 to 1.01.
Homologues: Orthologues: chimpanzee KHDC1 (100% identical), macaque KHDC1 (98% identical), mouse Khdc1c (43% identical), mouse Khdc1a (43% identical), rat LOC134483627 (43% identical), rat Khdc1 (41% identical), mouse Khdc1b (39% identical). Paralogues in human: KHDC1L (66% identical), DPPA5 (15% identical).
Diseases named in the same sentence as KHDC1 in open-access papers:
KHDC1 is named in the same sentence as 3 diseases in open-access papers, as found by Europe PMC text mining. Sharing a sentence is not in itself a finding about the gene and the disease. The quoted sentences say what the papers report.
osteoarthritis (1 paper, 2023). A noninflammatory degenerative joint disease occurring chiefly in older persons, characterized by degeneration of the articular cartilage, hypertrophy of bone at the margins and changes in the synovial membrane. "As a novel KHDC1 member, only one study is currently available in osteoarthritis synovial cells to unveil KHDC1L’s function of promoting proliferation." (PMID 36734243, 2023).
KHDC1 also shares sentences with these, for which no sentence is quoted: cancer (1 paper); tumor (1).